AMBP (alpha-1-microglobulin/bikunin precursor)
Diseases named in the same sentence as AMBP in open-access papers:
AMBP is named in the same sentence as 85 diseases in open-access papers, as found by Europe PMC text mining. Sharing a sentence is not in itself a finding about the gene and the disease. The quoted sentences say what the papers report.
Hypertension (5 papers, 2019 to 2025). The presence of chronic increased pressure in the systemic arterial system. "The upregulated circulating proteins in PE+ (AMBP, VTN, CLU, F2, PZP, APCS, and HBB) are involved in blood pressure regulation, extracellular matrix dynamics, and immune system function, highlighting the pathogenesis of this hypertensive disorder in the context of inflammation and immune defense." (PMID 40673030, 2025).
prostate carcinoma (5 papers, 2015 to 2023). A carcinoma that arises from epithelial cells of the prostate gland. "This study provided valuable insights into how AMBP could contribute to the tumorigenesis of prostate cancer, adding to the evidence of AMBP’s potential as a diagnostic and prognostic marker." (PMID 38201450, 2023). "This supported previous observations about the downregulation of AMBP in prostate cancer tissue and its potential involvement in disease development and progression." (PMID 38201450, 2023). "Their findings emphasized the relevance of AMBP as a biomarker, showing a significant difference in its expression between prostate cancer and benign samples." (PMID 38201450, 2023). "The cumulative evidence suggests that AMBP’s differential expression and involvement in various biological processes, including immune response modulation, might have direct implications in prostate cancer pathogenesis." (PMID 38201450, 2023). "Granulin, AMBP, CHMP4A, and CHMP4C were also higher in men with high GS prostate cancer (p-value < 0.05)." (PMID 28211531, 2017). "GRN, AMBP, CHMP4A, CHMP4C, and CHMP2 may play important roles in aggressive prostate cancer and may be potential targets of treatment." (PMID 28211531, 2017). "Among them, fatty acid binding protein 5 (FABP5), Alpha-1-Microglobulin/Bikunin Precursor (AMBP), Charged Multivesicular Body Protein 4A (CHMP4A), and Charged Multivesicular Body Protein 4C (CHMP4C) were significantly differentially expressed in prostate cancer patients compared to normal samples." (PMID 38201450, 2023). "For example, the protein AMBP (AMBP), which shows high levels in urine from patients with both HNSCC and thyroid cancer, has been found to also be secreted in urine from the bladder and prostate cancer patients and in other biofluids (such as cerebrospinal fluid and serum) of such patients." (PMID 30813269, 2019). "In a recent study, 2-D DIGE gel electrophoresis coupled with MS and bioinformatics analysis identified serotransferrin (TF), alpha-1-microglobulin/bikunin precursor (AMPB) and haptoglobin (α-chain) (HP) as new urinary biomarkers, which could distinguish between BPH and prostate cancer." (PMID 30197761, 2018).
atherosclerosis (4 papers, 2020 to 2023). A disease characterized by the build-up of fatty material and calcium deposition in the arterial wall resulting in partial or complete occlusion of the arterial lumen. "AMBP may be an atherosclerosis-promoting protein, but its downregulation during ischemia is associated with neuroprotective effects." (PMID 36959823, 2023).
lung carcinoma (4 papers, 2017 to 2023). "α-1-microglobulin/bikunin precursor (AMBP), peroxiredoxin 2 (PRDX2), and Parkinson’s disease protein 7 (PARK7) are three protein markers associated with lung cancers." (PMID 29597315, 2018). "AMBP, α2 macroglobulin and A1AT were shown to be endopeptidase inhibitor, which can promote the development of lung cancer." (PMID 36237335, 2022). "Higher concentrations of AMBP and PRDX2 markers were found in the lung cancer group compared to the control group (with a fold change (FC) of 3.4 and 2.0, respectively), whereas PARK7 concentration was lower (FC = 0.49)." (PMID 28300171, 2017). "The statistical results of the preclinical validation of the QDEM and xMAP® 3-plex immunoassays detecting AMBP, PRDX2, and PARK7 markers as tools for diagnosis of lung cancer were practically identical." (PMID 28300171, 2017). "In order to compare QDEM and xMAP® technologies, the same 3-plex immunoassay for the quantification of AMBP, PRDX2, and PARK7 lung cancer markers was developed for xMAP®." (PMID 28300171, 2017). "As in the QDEM-based analysis, the concentrations of AMBP and PRDX2 markers in the lung cancer group were found to be higher than in the control group (FCs of 5.30 and 2.62, respectively), whereas PARK7 concentration was lower (FC = 0.36)." (PMID 28300171, 2017). "By blood proteomic analysis, researchers found that AMBP, α2 macroglobulin, and SERPINA1 might be valuable biomarkers for early detection of lung cancer using serum from 20 NSCLC and 10 healthy donors, and it would be better to perform a clinical validation in a larger cohort." (PMID 37475010, 2023).
COVID-19 (3 papers, 2023 to 2024). A disease caused by infection with severe acute respiratory syndrome coronavirus 2. "We identified that protein alpha-1-microglobulin/bikunin precursor (AMBP) and alpha-2-macroglobulin levels weresubstantially reduced in the COVID-19-with the AVB group." (PMID 39076308, 2024). "α-1-Microglobulin/bikuninprecursor (AMBP), a plasma glycoprotein, is catalyzed to form α-1-macroglobulinthat regulates the inflammatory response but has not, to date, beenreported to modulate inflammation in COVID-19." (PMID 38048423, 2024).
diabetic nephropathy (3 papers, 2019 to 2024). "Further, microalbuminuria and diabetic nephropathy patients marked the excretion of Ig kappa chain V–II, protein 25, Ig lambda 2 chain region, Alpha 1 acid glycoprotein 1, Apolipoprotein A1, transthyretin/prealbumin, Ig kappa C chain region, AMBP, Cystatin C, zinc alpha 2 glycoprotein and Ubiquitin." (PMID 31131043, 2019).
breast carcinoma (2 papers, 2014 to 2024). "The low expression of Alpha-1-Microglobulin/Bikunin Precursor (AMBP) has been reported to increase tumor progression in prostate cancer and oral squamous carcinoma, but is relatively understudied in breast cancer." (PMID 38038766, 2024).
cholangiocarcinoma (2 papers, 2022 to 2026). A carcinoma that arises from the intrahepatic biliary tree (intrahepatic cholangiocarcinoma) or from the junction, or adjacent to the junction, of the right and left hepatic ducts (hilar cholangiocarcinoma). "Proteomic screening also found the overexpression of AMBP protein precursors in cholangiocarcinoma tissue." (PMID 36144640, 2022). "Thus, AMBP, NGAL, and PSMA3 are also promising potential biomarkers for cholangiocarcinoma." (PMID 36144640, 2022).
Endemic Nephropathy (2 papers, 2014 to 2025). "AMBP plays a role in inflammation and endemic nephropathy and can be used as a biomarker for early tubular dysfunction, In urine, AMBP acts as a trypsin inhibitor and radical scavenger." (PMID 41311872, 2025).
gastric cancer (2 papers, 2016 to 2023). A primary or metastatic malignant neoplasm involving the stomach. "Moreover, the aberrant expression of serum AMBP was previously identified in gastric cancer." (PMID 26993605, 2016).
glomerular disease (2 papers, 2014 to 2024). "In the current study, some of the presented biomarkers have reported before as already known proteins implicated in glomerular disease including: B2MG and AMBP, AFAM, but most of the other candidates identified in this study are novel." (PMID 25032130, 2014).
kidney damage (2 papers, 2014 to 2015). "Among the differentially expressed proteins previously identified, our study focused on UROM, AMBP and CYSC, since an ample literature provides evidence of their involvement in renal damage and nephropathy." (PMID 26272683, 2015).
kidney stones (2 papers, 2016 to 2026). "Recent studies show that AMBP may be a marker for differential diagnosis such as bowel disease, cancer and kidney stones." (PMID 27336623, 2016).
liver cancer (2 papers, 2025). An epithelial or non-epithelial malignant neoplasm that arises from the liver. "Antigenicity, molecular weight, subcellular localization and expression site predictions were used to shortlist liver cancer associated proteins including AMBP, CFB, CDHR5, VTN, APOBR, AFP, SERPINA1 and APOE." (PMID 39752339, 2025).
membranous glomerulonephritis (2 papers, 2013). A slowly progressive inflammation of the glomeruli characterized by immune complex deposits at the glomerular basement membrane, resulting in a thickened membrane, and nephrotic syndrome. "Proteins CERU, CO3, A2GL1, HEMO, RET4, AMBP and B2MG have been found among urinary biomarkers for lupus nephritis and membranous glomerulonephritis." (PMID 24339887, 2013).
mesothelioma (2 papers, 2023). A usually malignant and aggressive neoplasm of the mesothelium which is often associated with exposure to asbestos. "The association between AMBP gene expression and patient’s survival in thirty-two different cancer types was also investigated, showing a significant negative impact of high AMBP expression (expression value > 3rd quartile) in brain lower grade glioma (LGG), GBM, KIRP, mesothelioma (MESO), and THCA." (PMID 36414878, 2023).
Parkinson disease (2 papers, 2011 to 2022). A progressive degenerative disorder of the central nervous system characterized by loss of dopamine producing neurons in the substantia nigra and the presence of Lewy bodies in the substantia nigra and locus coeruleus. "In addition, Marco Sancandi and Stefania D’Alessio showed the presence of a citrullinated form of the AMBP protein in pre-motor Parkinson’s disease and health assessment in animal models." (PMID 35225987, 2022). "In our second search, we found a single gene, AMBP, which is differentially associated with Ibuprofen (and not with other NSAIDS), and which is associated with Parkinson disease (but not inflammation), based on a 1996 study which showed the potential of AMBP as a biomarker for the disease." (PMID 22162991, 2011).
renal dysfunction (2 papers, 2015 to 2022). "Other proteins involved in renal dysfunction, also tested in this study, were UROM, AMBP and CYSC." (PMID 26272683, 2015).
acute pancreatitis (1 paper, 2021). An acute inflammatory process that leads to necrosis of the pancreatic parenchyma. "At first, bikunin (also known as protein AMBP) was used as a model CSPG since it was relatively well characterized, available in large quantities from human urine and also used in some countries as a pharmaceutical agent to treat acute pancreatitis." (PMID 34490248, 2021).
Anxiety (1 paper, 2023). Intense feelings of nervousness, tension, or panic often arise in response to interpersonal stresses. "A previous study found that deletion of the alpha 1 microglobulin/bikunin precursor, which is necessary for the functional complex of ITIH1 or ITIH3, increases anxiety behavior, suggesting the involvement of Itih3 in mood disorders." (PMID 36794261, 2023).
cyst (1 paper, 2021). A sac-like closed membranous structure that may be empty or contain fluid or amorphous material. "Such comparison resulted in 4 upregulated (CP, CEACAM5, DMBT1, and KRT6A) and 8 downregulated (CEL, CPA1, CPB1, ALB, SERPINA4, CA2, CLU, and AMBP) DEGs secreted in cyst fluid of high-risk IPMNs." (PMID 34790815, 2021).
IgA nephropathy (1 paper, 2013). "One of the molecular functions of AMBP is IgA binding, but the role of this protein in pathogenesis of IgA nephropathy is still unknown." (PMID 24339887, 2013).
joint diseases (1 paper, 2022). "In a study by Reuben Gobezie, 18 differentially expressed proteins, including the AMBP protein, were identified in synovial fluid in joint diseases by using HPLC-MS/MS." (PMID 35225987, 2022).
lung diseases (1 paper, 2017). "A set of three most significantly upregulated proteins (HBB, CRP and SERPINA1) and four most significantly downregulated proteins (APOA2, AHSG, KNG1 and AMBP) were selected for validation in an independent cohort of IPF and other lung diseases using ELISA test." (PMID 28122020, 2017).
Obesity (1 paper, 2020). Accumulation of substantial excess body fat. "The reduced expression of AMBP in the HF fed groups during the early development of obesity requires further studies." (PMID 32709962, 2020).
sarcopenia (1 paper, 2026). Progressive decline in muscle mass due to aging which results in decreased functional capacity of muscles. "We identified seven robust protein signatures (LRG1, CST3, TIMP1, C2, ITIH1, AMBP and LYZ) that showed consistent significant associations with sarcopenia components in both cohorts." (PMID 41782349, 2026).
tumor (15 papers, 2008 to 2026). "Since tumor progression is tightly associated with re-arrangement of the extracellular matrix, employment of AMBP, ITIH1, and ITIH4 may also support the net benefit for early detection of CRC and designation of probable cell migration." (PMID 32023884, 2020). "In the BF-TK/GCV/BF-TK group, the top five hub proteins were AMBP, HRG, APCS, HPX, and GIG25; some proteins (HRG, HPX, and GIG25) are positively associated with tumor metastasis." (PMID 37511481, 2023). "Moreover, CD41, dipeptidyl peptidase IV (DPPIV), Wilm’s Tumour-1 (WT-1), and alpha-1-microglobulin/bikunin precursor (AMBP) are putative small EV urinary biomarkers that are associated with diabetic nephropathy." (PMID 36406206, 2022). "AMBP overexpression in CCA cells activated WNT molecules (β-catenin, c-Myc, and Cyclin D1), enhancing tumor progression." (PMID 41824874, 2026). "From the previous study of our group, the dysregulated proteins AMBP, KLK3, LMAN2, and TTR were found dysregulated in urine and tumor tissue from PCa patients, while SECTM1 was only found in urine from PCa patients, and CDH1 and EFEMP1 were only in PCa tissue." (PMID 35454907, 2022). "Two proteins higher in the tumor patients, as compared to healthy volunteers, resulted in additional increase after the infusion of BPA: Retinol-binding protein 4 (RBP4) and Protein AMBP (AMBP)." (PMID 30813269, 2019). "In primary HGSOC, the recurrent tumor-specific DEG IL7R exhibited a positive correlation with AMBP and HDGF and a negative correlation with FEN1, LRRC25, RIGI, and TBL1X (p < 0.05)." (PMID 41596598, 2026).
cancer (10 papers, 2008 to 2025). A tumor composed of atypical neoplastic, often pleomorphic cells that invade other tissues. "The reduced expression of AMBP in seven of ten cancers investigated, with respect to controls, may further support previous findings suggesting its involvement as anti-cancer and anti-metastatic agent." (PMID 36414878, 2023). "The function of the AMBP protein in cancer remains undisclosed." (PMID 35454907, 2022). "Both AMBP and SAP3 were found to increase also in our previous proteomic study conducted on urine samples from PCa patients with different risks of cancer progression." (PMID 37046536, 2023). "Still, there were several proteins which harbored very good statistics, but lacked previous evidence to link them to cancer status, such as Protein AMBP (alternative name, alpha-1-microglobulin), Multivesicular body subunit 12B and V-type proton ATPase 116 kDa subunit." (PMID 23284758, 2012).
kidney disease (6 papers, 2013 to 2024). "Literature research indicated physiological relevance with regard to kidney disease for two proteins (AMBP, DAPK1)." (PMID 31083566, 2019).
infection (4 papers, 2014 to 2022). The state of being infected such as from the introduction of a foreign agent such as serum, vaccine, antigenic substance or organism. "The alteration of proteins involved in blood coagulation was also found in 2 and 4 weeks after infection, namely complement factor H and protein AMBP." (PMID 35271623, 2022). "A study found that the AMBP gene was overexpressed in the amniotic fluid of women without intra-amniotic infection/inflammation." (PMID 36362120, 2022).
bacterial infection (1 paper, 2025). "Patients with bacterial infection had lower plasma levels of AMBP and ITIH2, an increase in ITIH3, while ITIH1 remained unchanged compared with healthy controls." (PMID 40885913, 2025).
AMBP also shares sentences with these, for which no sentence is quoted: preeclampsia (6 papers); hepatoma (4); leukemia (4); acute kidney injury (3); neuroendocrine tumors (3); oral squamous cell carcinoma (3); type 2 diabetic (3); Dent disease (2); diabetes (2); kidney injuries (2); thyroid cancer (2); acute lymphoblastic leukemia (1); anemia (1); Arthritis (1); asthma (1); bladder cancer (1); cardiovascular diseases (1); chronic kidney disease (1); focal segmental glomerulosclerosis (1); glomerulosclerosis (1); Graves disease (1); haemolytic anaemia (1); heart failure (1); Hepatic steatosis (1); hypersensitivity pneumonitis (1); Insulin resistance (1); intrauterine growth restriction (1); Intraventricular hemorrhage (1); invasive breast carcinoma (1); ischemia (1).
A further 24 diseases each share a sentence with AMBP in 1 paper.